PPARD (peroxisome proliferator activated receptor delta)
Diseases named in the same sentence as PPARD in open-access papers (continued):
Sharing a sentence is not in itself a finding about the gene and the disease.
psoriasis (26 papers, 2009 to 2025). An autoimmune condition characterized by red, well-delineated plaques with silvery scales that are usually on the extensor surfaces and scalp. "For example, overexpression of PPARδ in the epidermis causes a psoriasis-like skin disease featuring hyperproliferation of keratinocytes, dendritic cell accumulation, and endothelial activation." (PMID 23977003, 2013). "Topical application of toll-like receptor 7/8 agonist imiquimod, a commonly used murine psoriasis model, was shown to induce the expression of Alox8 along with PPARδ." (PMID 38637408, 2024). "The PPARD/Ppard gene is upregulated in lesional skin of patients with psoriasis vulgaris and of mouse models of psoriasis." (PMID 34298981, 2021). "On the other hand, the activation of PPARδ with tetradecylthioacetic acid (TTA) also showed beneficial effects in psoriasis." (PMID 34298981, 2021). "To date, the therapeutic effects of PPARδ targeting in atopic dermatitis and psoriasis remain underinvestigated." (PMID 34298981, 2021). "An important parameter for the topical utilization of drugs targeting PPARδ to alleviate atopic dermatitis and psoriasis is their transdermal absorption and ability to passage into the bloodstream." (PMID 34298981, 2021). "In vitro experimental models of psoriasis showed that the expression of other PPARs (PPARa) was also decreased in the skin, while PPARb and PPARd expressions were increased." (PMID 33133175, 2020). "Some studies revealed that PPARδ activators cause inflammation in the UVB-damaged skin through TGF-β1 mediated responses and psoriasis in the mouse skin." (PMID 29619069, 2018). "We and others have recently shown that PPARδ is overexpressed in human psoriatic as well as in murine psoriasis-like skin lesions, and that treatment with delphinidin, another VDR ligand, normalized the expression in a preclinical mouse model of psoriasis." (PMID 29401702, 2018). "In lesional skin of patients with psoriasis and atopic dermatitis the expression of PPARD was also increased while the expression of PPARA and PPARG was decreased." (PMID 21573029, 2011). "The EGF-family ligand TGF-α (Tgfa) and the kinase Ptk6, which are also increased in both psoriasis and PPARδ transgenic mice, were elevated in SKO mice as well." (PMID 21573029, 2011). "We have recently reported a key role of PPARδ signaling in the pathogenesis of AD and potentially of psoriasis, by up-regulating peroxisomal ß-oxidation via ACOX1, which contributes to shortening of SC lipid species, thereby initiating or perpetuating epidermal barrier impairment in AD." (PMID 35216234, 2022). "The role of PPARδ has been less investigated in atopic dermatitis than in psoriasis." (PMID 34298981, 2021). "The expression of FABP5 parallels that of PPARδ in psoriasis and atopic dermatitis." (PMID 34298981, 2021). "Consequently, topical treatment with an irreversible PPARδ antagonist would be more appropriate to alleviate psoriasis symptoms." (PMID 34298981, 2021). "PPARδ has been shown to be involved in wound healing, which might demonstrate relevance in both psoriasis and atopic dermatitis." (PMID 34298981, 2021). "The expression of FABP5 parallels that of PPARδ at both the mRNA and protein levels in psoriasis." (PMID 34298981, 2021). "Indeed, a single topical treatment with GSK3787, which covalently binds and permanently inactivates PPARδ showed similar therapeutic efficacy as several topical applications with GSK0660 in mice with psoriasis-like skin inflammation." (PMID 34298981, 2021). "However, Lcn2 is also increased in lesional compared to non-lesional skin samples from psoriasis patients, as well as increased in the skin of a murine model of PPARδ hyperactivation with a psoriasis-like condition." (PMID 21573029, 2011).
psoriasis (continued). "Interestingly, transgenic mice that overexpress PPARδ develop a psoriasis-like inflammatory skin disease upon ligand activation featuring hyperproliferation of keratinocytes, dendritic cell accumulation, and endothelial cell activation." (PMID 21573029, 2011). "Wnt5a signalling in psoriasis may also be related to the activation of the nuclear hormone receptor PPARδ which we have previously identified as a central mediator in psoriasis." (PMID 19399181, 2009). "However, although PPARD has been identified as a putative pathogenic gene in psoriasis, variants at the PPARD genomic locus have not been associated with psoriasis." (PMID 34298981, 2021). "However, in lesional psoriasis, p65 NF-kB is sequestered in the cytoplasm of basal KCs, which might allow PPARδ to exert its transcriptional regulation on various genes, including those involved in KC proliferation." (PMID 34298981, 2021). "The reversibility of the PPARδ agonist-induced effect by the synergistic action of a PPARδ agonist and antagonist was also described in skeletal muscle cells (C2C12 line), in a mouse model of psoriasis, and in human umbilical vein endothelial cells (HUVEC)." (PMID 37175437, 2023). "Indeed, OVOL1 controls the expression of FLG and a recent study revealed that lipid metabolism is the most altered metabolic pathway, with the notable up-regulation of PPARδ, in OVOL1 knock-out mice treated with imiquimod to induce psoriasis-like inflammation." (PMID 35216234, 2022). "Thus, given the role of PPARδ in psoriasis and atopic dermatitis, PPARδ antagonism, rather than activation, might be the preferred therapeutic approach to treat both diseases." (PMID 34298981, 2021). "However, an enhanced PPARδ pathway induced by an impaired epidermal barrier might significantly contribute to ACOX1 upregulation in both ADL- and psoriasis-like inflammation." (PMID 34909730, 2021).
hepatocellular carcinoma (24 papers, 2008 to 2025). A malignant tumor that arises from hepatocytes. "In liver cancer, Ppard−/− mice were more susceptible to developing induced hepatocellular carcinoma (HCC) and, accordingly, PPARD overexpression in HCC cell lines inhibited proliferation, migration, and invasion while enhancing apoptosis in these cells." (PMID 41148824, 2025). "In patients with advanced hepatocellular carcinoma, higher levels of m1A modification of tRNAs have been associated with increased PPARδ translation efficiency, leading to elevated cholesterol synthesis and activation of the Hedgehog pathway." (PMID 40809690, 2025). "For tRNA, m1A modification promotes partial tRNA methylation in hepatocellular carcinoma, leading to increased translation of PPARδ and impacting cholesterol synthesis." (PMID 40809690, 2025). "Given that PPARδ potential role in hepatocellular carcinoma (HCC) is still obscure, we comprehensively assessed its expression pattern, prognosis, functions and correlation with tumor microenvironment in HCC using public database data and in vitro studies." (PMID 35151320, 2022). "COX-2 and peroxisome proliferator-activated receptor delta are involved in important growth promoting signaling pathways in human hepatocellular carcinoma." (PMID 29098441, 2017). "We first confirmed the suppression of PPARδ both in LR and human hepatocellular carcinoma at protein level, and then demonstrated that PPARδ agonist GW501516 reduces the proliferative potential of hepatoma cells." (PMID 25116592, 2014). "The study showed that the m1A methyltransferase complex (TRMT6 and TRMT61A) could increase PPARδ translation, which in turn triggers cholesterol synthesis to activate Hedgehog signaling in human hepatocellular carcinoma cell lines." (PMID 36035160, 2022). "In rodents, however, fibrate drugs cause hepatomegaly and eventually hepatic carcinoma, which is not seen in humans, and is reflected in a much lower level of expression of PPARα and thus a different balance between PPARα and PPARδ in the human liver." (PMID 22550474, 2012). "Extended further, VLDL stimulation of HL-expressing HUVECs and FAO hepatoma cells increased mRNA expression of canonical PPARδ target genes, including adipocyte differentiation related protein (ADRP), angiopoietin like protein 4 and pyruvate dehydrogenase kinase-4." (PMID 21750705, 2011). "A selective PPARδ agonist (GW501516) has been shown to stimulate proliferationof human breast, prostate, and hepatocellular carcinoma cells." (PMID 18551185, 2008). "To test the hypothesis that PPARδ could reduce the proliferative capacity of cancer cell lines, we administered GW501516 (10 nM) to proliferating hepatoma cells (i.e. Hepa 1–6)." (PMID 25116592, 2014). "In addition, COX-2-derived PGl2 directly transactivatesPPARδ, and COX-2-derived PGE2 indirectly induces PPARδ activation in CRC, hepatocellular carcinoma,and cholangiocarcinoma cells." (PMID 18551185, 2008). "We thus pointed to PPARδ down-regulation to validate our approach, with the aim of understanding if PPARδ suppression is confirmed also in HCC, and if it could negatively modulate hepatoma cells growth." (PMID 25116592, 2014).
endothelial dysfunction (22 papers, 2012 to 2025). In vascular diseases, endothelial dysfunction is a systemic pathological state of the endothelium (the inner lining of blood vessels) and can be broadly defined as an imbalance between vasodilating and vasoconstricting substances produced by (or acting on) the endothelium. "At the same time, H2S also improves the endothelial dysfunction by activating the PPARδ/eNOS pathway to regulate hypertension." (PMID 40732205, 2025). "PCB2 on ER stress and endothelial dysfunction required the inter-dependent actions of PPARδ and AMPK." (PMID 39995417, 2025). "H2S also improves endothelial dysfunction in renal hypertension by activating peroxisome proliferator activated receptor delta (PPARδ) and inhibiting BMP4/COX-1 pathways." (PMID 36358508, 2022). "PPARδ also regulates glucose homeostasis, as well as protects against atherosclerosis and endothelial dysfunction." (PMID 34439415, 2021). "In summary, this study provided evidence that OA, a component of pentacyclic triterpenes, is a natural modulator of PPARδ and ameliorates the high glucose impaired endothelial dysfunction." (PMID 28067284, 2017). "H2S ameliorates endothelial dysfunction through the anti-inflammatory effect of the PPARδ/SGLT2/p-STAT3 signaling pathway in senescent ECs and may be a potential therapeutic target for anti-ageing treatment." (PMID 37587757, 2023). "Furthermore, PPARδ is involved in the restoration of endothelial dysfunction, and vasodilation in animals fed a high-fat diet." (PMID 37168052, 2023). "In addition, endothelial dysfunction in aortas of endothelial cell-specific Pparδ−/− mice was also attributed to elevated ROS levels." (PMID 26649033, 2015).
Hyperglycemia (22 papers, 2007 to 2025). An increased concentration of glucose in the blood. "We investigated PPARδ-responsive molecules associated with premature senescence induced by hyperglycemia in ARPE-19 cells, a cell line derived from the normal eyes of a 19-year-old male." (PMID 35740104, 2022). "Based on its potential role in regulation of cellular senescence, the possible beneficial effects of PPARδ on aging processes of RPE cells implicated in hyperglycemia-associated retinal damage must be evaluated." (PMID 35740104, 2022). "Decreased cardiac PPARδ expression has been identified in rats that exhibit diabetic cardiomyopathy, and the reduction of PPARδ expression in cardiac cells during hyperglycemia has been found to be associated with higher reactive oxygen species (ROS) production." (PMID 28672855, 2017). "In experimental ICH models, melatonin has also been associated with improved motor outcomes and the preservation of the corticospinal tract, along with the attenuation of hyperglycemia-induced brain injury via the PPARδ/PGC-1α pathway." (PMID 40095798, 2025). "The upregulation of SIRT1 by PPARδ is a critical event in the blockade of hyperglycemia-induced premature senescence of ARPE-19 cells." (PMID 35740104, 2022). "We found that GW501516-activated PPARδ suppresses hyperglycemia-triggered premature senescence of ARPE-19 cells by upregulating SIRT1, which has been implicated in the modulation of lifespan." (PMID 35740104, 2022). "Consistently, the present study showed that activation of PPARδ by the specific ligand GW501516 significantly attenuated hyperglycemia-triggered ROS generation in ARPE-19 cells." (PMID 35740104, 2022). "The findings of the present study provide new insight into the primary role of PPARδ as an anti-senescence factor that inhibits hyperglycemia-triggered premature senescence of RPE cells." (PMID 35740104, 2022). "Our observations suggest that activation of PPARδ by a specific ligand attenuates hyperglycemia-triggered premature senescence of RPE cells via upregulation of SIRT1, which reduces cellular ROS accumulation." (PMID 35740104, 2022). "Activation of the PPARδ pathway also mitigates hepatic gluconeogenesis, resulting in amelioration of hyperglycemia." (PMID 30213948, 2018). "Taken together, telmisartan reversed the hyperglycemia-induced cardiac fibrosis through the PPARδ pathway instead of the AMPK pathway." (PMID 27519769, 2016). "Although the function of members of the nuclear receptor PPAR family in cellular senescence is controversial, the present study clearly demonstrates that activation of PPARδ by a specific ligand attenuates hyperglycemia-triggered premature senescence of RPE cells." (PMID 35740104, 2022). "Given that the expression of PPARδ target genes is involved in pathological changes, ligands that activate PPARδ might be key for controlling hyperglycemia-triggered cellular senescence." (PMID 35740104, 2022). "Previous studies have indicated that inhibitors of reactive oxygen species (ROS) production or mitogen-activated protein kinase (MAPK) activation are involved in the reduction of cardiac PPARδ expression in response to hyperglycemia in hepatocytes and adipocytes." (PMID 27519769, 2016). "Telmisartan improved the hyperglycemia-induced cardiac fibrosis through the PPARδ/STAT3 pathway." (PMID 27519769, 2016). "However, in contrast to above finding, we found that the overexpression of STAT3 directly downregulated PPARδ independent from the stimulation of hyperglycemia." (PMID 27519769, 2016). "Moreover, we demonstrated a novel finding that Rh2 may activate PPARδ to inhibit these fibrotic signals to ameliorate the impaired heart function and cardiac fibrosis induced by hyperglycemia." (PMID 28672855, 2017).
Hyperglycemia (continued). "In the present study, for the first time, we demonstrated that ginsenoside Rh2 may alleviate cardiac fibrosis induced by hyperglycemia both in vivo and in vitro and identified that the effect of Rh2 is mainly induced via mediation of the PPARδ signaling pathway." (PMID 28672855, 2017). "To conclude, telmisartan works through PPARδ, instead of the AMPK pathway, to suppress the hyperglycemia-enhanced expression of STAT3/CTGF/MMP9 and the subsequent cardiac fibrosis (Graphic abstract)." (PMID 27519769, 2016). "Furthermore, resveratrol, an activator of SIRT1, mimicked the anti-senescence action of GW501516 in hyperglycemia-exposed ARPE-19 cells, indicating that PPARδ inhibits cellular senescence by upregulating SIRT1." (PMID 35740104, 2022). "Notably, without the condition of hyperglycemia, GW0742 failed to increase the expression of PPARδ or to affect the subsequent fibrosis-associated proteins." (PMID 27519769, 2016).
Hypertension (22 papers, 2008 to 2025). The presence of chronic increased pressure in the systemic arterial system. "In a study where several in vitro cell cultures were used, 6-GN was reported to normalize the expression of major biomarkers related to hypertension through the peroxisome proliferator-activated receptor delta (PPARδ)." (PMID 35585878, 2022). "6-Gingerol ameliorated the expression of biomarkers involved in the development of hypertension through PPARδ in HUVECs, HEK293, and differentiated 3T3-L1 cells." (PMID 30643517, 2018). "While the potential anti-hypertensive effect of activating PPARδ post additional beneficial effect when treating heart failure patients with hypertension, other systemic effects of PPARδ remain major confounding factors preventing the potential application." (PMID 31032335, 2018). "Buspirone may induce the losses of body weight and abdominal fat weight through the activation of PPARδ dependent catabolic metabolism producing energy, and eventually, the ameliorated lipid metabolism could normalize high blood pressure." (PMID 37168052, 2023). "This study provided new insights into the beneficial role of H2S on blood vessels and suggested PPARδ may be a new target for hypertension therapy." (PMID 33318871, 2021). "Based on this observation and our previous findings concerning the protective effects of PPARδ in the vasculature, we hypothesized that ligand-activated PPARδ may affect Ang II-induced vascular hypertrophy, a critical phenotype in hypertension." (PMID 30620754, 2019). "Because many studies have reported a close correlation between NAFLD and cardiovascular diseases such as hypertension and atherosclerosis, we investigated the effect of A. glehni on nonalcoholic fatty liver in atherosclerotic mice and it was conducted with focusing on PPARδ." (PMID 29201040, 2017). "There are three PPAR subtypes—PPARα, PPARδ (also known as PPARβ), and PPARγ, which regulate gene expression in a variety of process, including lipid and glucose metabolism, atherosclerotic plaque formation, cellular differentiation, angiogenesis, inflammation, hypertension, and heart failure." (PMID 20613990, 2010). "PPARδ could increase endothelial nitric oxide synthase (eNOS) production by activating phosphoinositide 3-kinase/protein kinase B (PI3K/Akt) or 5′ adenosine monophosphate-activated protein kinase (AMPK) signaling pathway in renal arterial endothelium of spontaneous hypertension rats." (PMID 33318871, 2021).
prostate carcinoma (22 papers, 2006 to 2025). A carcinoma that arises from epithelial cells of the prostate gland. "Genetic suppression of PPARδ inhibits tumor growth of prostate cancer cells, however, some of the studies have reported the anticancer activity of PPARβ/δ agonists." (PMID 34775964, 2021). "PPARδ induces xenograft tumor growth of prostate cancer cells by regulating the ATP binding cassette transporter 1 (ABCA1) gene." (PMID 34775964, 2021). "Inferring that PPARD also represses NCOA2's activity, provides another clue for PPARD's inactivation in prostate cancer progression." (PMID 19640296, 2009). "For instance, while ligand-independent activation of PPAR-δ exerted tumor suppressive functions in prostate cancer by repressing trefoil factor 1 (TFF1), PPARD expression has been correlated with cancer progression, angiogenesis, and metastasis in several cancers." (PMID 41148824, 2025). "We found by in vitro assay that the growth of intestinal cells was stimulated by the introduction of PPARδ cDNA (data not shown, our unpublished data), findings that are consistent with other reports that PPARδ enhances the in vitro growth of breast and prostate cancer cells." (PMID 16969348, 2006).